AIRE (autoimmune regulator)
Diseases named in the same sentence as AIRE in open-access papers (continued):
Sharing a sentence is not in itself a finding about the gene and the disease.
autoimmune disease (continued). "In the subset of patients with a clinical diagnosis of APECED who have wild-type AIRE genotype, it will be important to examine whether mutations in these or other AIRE regulators and/or partners may underlie their autoimmune disease." (PMID 34790633, 2021). "Overall, these immunologic abnormalities may contribute to the increased risk of infections and autoimmune diseases in DS patients altered thymic expression of the autoimmune regulator (AIRE) gene." (PMID 32973676, 2020). "The discovery that mutations in the autoimmune regulator (AIRE) gene cause the autoimmune-polyendocrinopathy-candidiasis-ectodermal-dystrophy (APECED) syndrome provided the novel concept that a monogenic defect can cause a systemic human autoimmune disease." (PMID 31849949, 2019). "Whether this is a direct effect of the thymic AIRE-deficiency or secondary to the severe autoimmune diseases in these patients remains unknown." (PMID 24592265, 2014). "The relevance of AIRE in regulating adaptive immune tolerance is underscored by the evidence that AIRE mutations contribute to the onset of a wide spectrum of organ-specific autoimmune diseases, among which are systemic sclerosis, rheumatoid arthritis (RA), and others." (PMID 37762419, 2023). "Therefore, loss‐of‐function mutations in AIRE result in a multisystem autoimmune disease." (PMID 32994995, 2020). "On the other hand, APS-1 diagnosis should be suspected and the AIRE gene studied in cases of childhood chronic candidiasis and/or hypoparathyroidism that is otherwise unexplained, especially when these clinical features are associated with other autoimmune diseases." (PMID 24988226, 2014). "Here, we expand the spectrum of variants in AIRE’s PHD domains associated with autoimmune diseases, describing patients harboring heterozygous mutations within the PHD1 and PHD2 domains of AIRE." (PMID 37235056, 2023). "The genetic and phenotypic characterization of patients and their families emphasize AIRE’s critical role in central immunological tolerance induction and indicates a correlation between autoimmune disease and AIRE function." (PMID 37235056, 2023). "In the case of AIRE gene defects, autoreactive T cells are discharged into the bloodstream, leading to the development of several autoimmune diseases." (PMID 37189748, 2023). "Autoimmune regulator (AIRE) is a protein encoded by the AIRE gene, a potent repressor of autoimmunity, and it can cause severe autoimmune disease when it mutates." (PMID 35370680, 2022). "In conclusion, we suggest that further analyses should be pursued to establish a novel link between organ‐specific autoimmune disease and dysregulated AIRE expression in clinical settings." (PMID 35313042, 2022). "It has also been shown that some AIRE mutations located in the SAND and PHD1 domains have a dominant negative effect on wild type AIRE, leading to common forms of autoimmune diseases (incl." (PMID 34145262, 2021). "Autosomal dominant (AD) AIRE mutations in the first plant homeodomain (PHD1) zinc finger domain and in the SAND domain have been described to cause organ-specific autoimmune disease resulting in milder phenotypes with reduced penetrance." (PMID 33584685, 2020). "A recent study showed that in females, estrogen induces epigenetic changes in the autoimmune regulator (AIRE) gene, causing reduced AIRE expression below a threshold that increases female susceptibility to autoimmune diseases and in particular MG." (PMID 32153563, 2020). "APECED patients with deficient autoimmune regulator (AIRE) gene collectively display a broad repertoire of high titer autoantibodies, including some which are pathognomonic for major autoimmune diseases." (PMID 28861084, 2017). "The female predominance observed in many autoimmune diseases may be partly explained by estrogens, which reduce the expression of the autoimmune regulator (AIRE) gene in the thymus." (PMID 41008338, 2025).
autoimmune disease (continued). "Different AIRE gene mutations cause APECED, whereas polymorphisms and some variants may be implicated in development of other more frequently autoimmune diseases." (PMID 39440452, 2024). "Autoimmune diseases are more prevalent in this group, possibly due to the AIRE gene on chromosome 21 and enhanced interferon (IFN) receptor expression, which may predispose them to conditions such as vitiligo and AA." (PMID 39373295, 2024). "Although rs2075876 G/A and rs760426 A/G exist in non-coding intronic regions, they have been implicated in inhibiting AIRE gene expression, thereby impairing thymic negative selection and increasing the risk for autoimmune disorders." (PMID 36902438, 2023). "AIRE polymorphisms have been associated with sporadic vitiligo and rheumatoid arthritis (RA) but not with other common autoimmune diseases such as T1D." (PMID 33537838, 2021). "On the other hand, the expression of AIRE and its target genes is suppressed by oestrogens, which may explain the gender bias of several autoimmune diseases." (PMID 33537838, 2021). "Functional AIRE gene mutation causes autoimmune polyendocrinopathy-candidiasis-ectodermal dystrophy (APECED), the main clinical manifestation of which is severe multiple organ-specific autoimmune disorders in humans." (PMID 33679804, 2021). "Despite the fact that rs2075876 (G>A) and rs760426 (A>G) are located in the intronic region, polymorphisms of AIRE gene noncoding regions have been reported to impair the thymic negative selection, hence, increasing the susceptibility to autoimmune diseases." (PMID 34621318, 2021). "AIRE represents the first single‐gene defect resulting in a multisystem autoimmune disease." (PMID 32994995, 2020). "Hence, in the context of previous studies, our results do not infer a final relationship between AAD development and the studied SNPs, but again point to the AIRE locus as a factor in autoimmune disease, beyond recessive APS1." (PMID 29849176, 2018). "We also showed that the AIRE gene, responsible for negative selection of T cells and implicated in a broad range of autoimmune diseases was upregulated in anti-Yo PCD OT (logFC 1.62, p < 0.001)." (PMID 29899393, 2018). "Furthermore, the transcription factor AIRE is part of the hepatic composite module and a key regulator in autoimmune diseases." (PMID 29296203, 2017). "Knocked-out mice and those carrying mutations or overexpressing ubiquitin ligases and deubiquitinases [such as autoimmune regulator (AIRE), Itch, Nedd4, Roquin, Cbl-b, TNFR-associated factor 6 (TRAF6), Act1, Peli1, NEDD4-family interacting protein 1 (Ndfip1), A20, CYLD] develop autoimmune diseases." (PMID 24917867, 2014). "Autoimmune regulator (AIRE), for which loss of function mutations cause an inherited human autoimmune disease, is expressed in mTECs and promotes TSA expression, thereby suppressing the onset of autoimmune diseases." (PMID 22969770, 2012). "On the basis of these data, the AIRE gene may be a candidate gene for several autoimmune disorders." (PMID 36902438, 2023). "Because the minor allelic frequency of some of these mutations (e.g., p.V301M, p.R303Q) is relatively high in the general population, genetic variation in AIRE may contribute to the development of organ-specific autoimmune diseases with a greater frequency than previously anticipated." (PMID 34790633, 2021). "Autoimmune Regulator (AIRE) gene is one of the key genes that regulate immune tolerance, making it a candidate for better understanding the pathogenesis of autoimmune disorders." (PMID 36902438, 2023). "It has also been shown that in C57BL/6 mice, AIRE deficiency was not sufficient to cause severe disease because they were also regulated by PD-1-mediated peripheral tolerance, whereas AIRE and PD-1 deficient mice suffered a rapid, multiorgan, and fatal autoimmune disease." (PMID 36009272, 2022).
autoimmune disease (continued). "Candidate gene mapping involving variant annotation, finemapping, and colocalisation analyses, and data from mouse models highlights the involvement of genes with a known role in autoimmune disease (PTPN22, HLA, IL2RA, and AIRE)." (PMID 34145262, 2021). "The thymic transcription factor autoimmune regulator (AIRE) plays a fundamental role in central tolerance induction, as it controls the transcription of genes coding for TRAs, and is predisposed, when not working properly, to favor the development of autoimmune disease." (PMID 26136751, 2015). "As AIRE is involved in the mechanisms of self-tolerance and APECED patients develop a wide number of autoimmune diseases, one would expect that APECED patients are prone to develop a larger variety of autoimmune diseases." (PMID 23781320, 2013). "The AIRE gene is also responsible for Autoimmune polyendocrinopathy syndrome, type I (APECED), an autosomal recessive autoimmune disease relatively common in Sardinia (OMIM # 607358)." (PMID 22291609, 2012). "In the absence of functional AIRE, human patients and mice develop multi-organ autoimmune disease due to a defect in thymic negative selection." (PMID 29849988, 2018). "The emergence of AIRE+ and FOXP3+ cells after thymocyte co-culture also raises the possibility that iTECs could support negative selection and Treg generation, which will be an important avenue to explore for applications to autoimmune diseases." (PMID 40855082, 2025). "Moreover, many studies demonstrated that thymus of AIRE knockout mice appears normal in terms of thymocytes number, but AIRE knockout mice and autoimmune polyendocrinopaythy-candidiasis-ectodermal dystrophy (APECED) patients, both exhibits autoimmune disease." (PMID 29069728, 2017). "The identification of the autoimmune regulator (AIRE) gene, a member of the zinc-finger gene family, led to an extremely important advancement in our knowledge of the central role played by a thymus dysfunction in the pathogenesis of organ-specific autoimmune diseases." (PMID 24137108, 2013). "Thus, AIRE is a good functional candidate in autoimmune diseases regardless of the population." (PMID 29849988, 2018).
thymoma (33 papers, 2011 to 2026). A neoplasm arising from the epithelial cells of the thymus. "Emerging data suggest that autoimmune regulator (AIRE) deficiency, frequently observed in thymomas, increases sensitivity to immune checkpoint blockade." (PMID 38611047, 2024). "AIRE deficiency, reduction in myoid cells, and failure in Treg generation are the main intra-thymoma alterations predisposing to the development of MG." (PMID 39329732, 2024). "Previous studies have shown that the mutilation of the autoimmune regulator (AIRE) gene was associated with thymoma-related MG." (PMID 31736858, 2019). "High titer AAbs to type 1 IFNs have also been described in APS-1, resulting from mutations in the AIRE gene that directs the development of self-tolerance, and in association with thymoma that constitute an autoimmunogenic environment." (PMID 31557985, 2016). "The loss of AIRE expression and intense p63 expression have been reported in human thymomas and thymic carcinomas." (PMID 26101855, 2015). "Loss of AIRE expression and gain of ΔNp63-α and -β isoform expression in the microscopic lesions, as well as in the manifest thymomas, appear to be common features between this mouse model and human thymomas." (PMID 26101855, 2015). "The reduced expression of AIRE may play a crucial role in the pathogenesis of the autoimmune paraneoplastic syndromes frequently associated with thymoma." (PMID 23577124, 2013). "It has been hypothesized that thymoma-associated AIRE deficiency may impair the tolerance to AChR and other antigens." (PMID 23125865, 2012). "Leaving aside the autoimmune phenomena, the hypothesis that AIRE deficiency may contribute in thymomas to the tumor-promoting antiapoptotic features of TECs should not be discharged." (PMID 23125865, 2012). "AIRE deficiency may, however, act indirectly on thymic B cells, for example by hyperactivity of functionally competent thymic γδ cells that may likewise be dysregulated in thymoma." (PMID 27426947, 2016). "In this study, we found that the medullary epithelial marker AIRE was found to help differentiate B3 from A thymomas." (PMID 36797681, 2023). "Accordingly, lower CHRNA1 mRNA levels were associated with significantly reduced AIRE mRNA levels in our MG thymoma samples, and with slightly reduced AIRE mRNA levels in hyperplastic MG thymuses." (PMID 36979710, 2023). "We found that CHRNA1 (AChR-α subunit) and AIRE (autoimmune regulator) genes were expressed at lower levels in hyperplastic and thymoma MG compared to the control thymuses, and that the RYR1 and TTN levels were decreased in MG versus the non-MG thymomas." (PMID 36979710, 2023). "The level of AIRE mRNA in type A, AB, and B1 thymoma was significantly higher than that in the B2, B3, and C (thymic carcinoma) thymoma." (PMID 36797681, 2023). "Of note, reduced intra-thymic CHRNA1, as well as AIRE, mRNA levels were observed in both corticosteroid-naïve and -treated MG thymoma patients, but only in corticosteroid-naïve patients with follicular hyperplastic thymuses." (PMID 36979710, 2023). "Thymoma, likely via the AChR it contains and the defective autoimmune regulator (AIRE) or HLA class II expression, is believed to be involved in the induction of MG in thymoma-MG." (PMID 36830985, 2023). "In both thymoma and immunodeficiency caused by RAG1 or RAG2 mutations, thymic deficiency of AIRE has been documented." (PMID 29651287, 2018). "For example, it is known that the autoimmune regulator (AIRE) gene is hypomethylated in thymomas, and that both DNA and histone tail methylation marks regulate AIRE expression." (PMID 27999265, 2016). "The thymus shows normal-for-age atrophy but is characterized by a paucity of muscle-like myoid cells, which may contribute to the generation of muscle-directed autoantibodies, and autoimmune regulator-positive TECs, as can be found in thymomas." (PMID 41008338, 2025).
thymoma (continued). "In this study, we aimed to explore the expression of thymic cortical epithelial markers (β5t, PRSS16, and cathepsin V) and medullary epithelial markers (claudin-4, CD40, and AIRE) in thymoma and TSCC and its correlation with histological classification, staging, and prognosis." (PMID 36797681, 2023). "Indeed, we found a positive correlation between CHRNA1 and AIRE expression levels in both hyperplastic thymuses and thymomas." (PMID 36979710, 2023). "Taken together, these data suggest that a lower CHRNA1 and AIRE expression in MG thymuses, particularly thymomas, could signify relevant molecular alterations contributing to anti-AChR autosensitization." (PMID 36979710, 2023). "To confirm the AIRE expression in TCs and other thymomas, we utilized RNA‐seq data from TCGA‐THYM." (PMID 36912123, 2023). "Thymoma is characterized by a deficit in the autoimmune regulator (AIRE) in neoplastic TEC." (PMID 35406782, 2022). "Moreover, in concert with reduced levels of AIRE, these alterations result in defective generation of regulatory T cells by thymomas." (PMID 26886206, 2016). "The thymomas that developed in the Tg1 and Tg4 mice reflect the expression levels of the ΔN64Ctnnb1/ERT2 transgene and share histological appearance (e.g. cellular atypia and perivascular space) and expression patterns of cellular markers (AIRE, p63, p21 and β5t) with those of human thymomas." (PMID 26101855, 2015). "Interestingly, the expression of AIRE, an autoimmune regulatory gene, is commonly down-regulated in thymoma." (PMID 23577124, 2013). "Interestingly, approximately 95% of thymomas lack AIRE expression." (PMID 41461613, 2026). "Interestingly, anti-IL-17 and anti-IL-22 antibodies were also found in CMC patients with thymomas with aberrant expression of AIRE, suggesting that dysregulation of central tolerance drives the generation of anti-cytokine antibodies and subsequent CMC development." (PMID 31548517, 2017). "Defective expression of the AIRE gene and MHC class II molecules in thymomas further impairs negative selection, compounding the loss of self-tolerance." (PMID 41008338, 2025). "Moreover, the decreased expression of autoimmune regulator (AIRE) and forkhead box protein P3 (FOPX3), which play a crucial role in preventing autoimmune responses, can also be observed in thymoma." (PMID 39318549, 2024). "More recently, using microarray profiling, Guo and colleagues demonstrated lower transcriptional levels of CHRNA3 and AIRE in MG compared to non-MG thymomas." (PMID 36979710, 2023). "In our results, the expression rate of AIRE in type A thymoma was 100%, while in B3 thymoma it was completely negative." (PMID 36797681, 2023). "Liu and colleagues reported a lower CHRNA1 and AIRE expression in MG thymomas, mainly of types B2 and B3, compared to non-MG thymomas." (PMID 36979710, 2023). "In facts although AIRE expression in thymomas is clearly decreased in terms of AIRE mRNA and AIRE+ cells, this datum does not correlate with the prevalence of myasthenia gravis." (PMID 23125865, 2012). "We found that the AIRE mRNA levels were not altered in hyperplastic MG compared to control thymuses, but they were significantly lower in MG thymomas, for both corticosteroid-naïve and -treated patients, compared to non-MG thymomas, control thymuses, and hyperplastic MG thymuses." (PMID 36979710, 2023). "Since CHRNA1 expression is controlled by AIRE, which is defective in thymomas, a reduction in CHRNA1 expression rather than an increase in these pathological tissues could be expected." (PMID 36979710, 2023). "On the other hand and again across all major histotypes, almost all thymomas show a reduced intratumoral generation of regulatory T cells (Tregs), attenuated MHC class II expression, and deficient expression of the autoimmune regulator, AIRE irrespective of MG status." (PMID 32373124, 2020). "Therefore, we determined the expression of AIRE and p63 in Tg1 thymoma samples and non-Tg thymi using co-immunofluorescence." (PMID 26101855, 2015).
thymoma (continued). "RYR1 was also down-regulated in thymomas from anti-RYR1 antibody-positive MG patients with B3/B3 mixed thymomas, who showed a down-regulation of AIRE and an up-regulation of RYR3, compared to thymomas of the same type in seronegative non-MG patients." (PMID 36979710, 2023).
autoimmune polyglandular syndrome type 1 (31 papers, 2013 to 2024). "Polyglandular autoimmune syndrome type 1, also known as autoimmune polyendocrinopathy-candidiasis-ectodermal dystrophy (APECED), is a rare immunodeficiency syndrome due to mutation of the autoimmune regulator gene (AIRE)." (PMID 34692360, 2021). "Furthermore, neutralizing autoantibodies to IL‐17A, IL‐17F, and IL‐22 are associated with an increased susceptibility to C. albicans infections in patients with autoimmune polyglandular syndrome type 1 (APS1) due to mutations in autoimmune regulator (AIRE)." (PMID 32609955, 2020). "Autoimmune regulator (AIRE), whose gene mutation is considered to be a causative factor of autoimmune polyglandular syndrome type 1 (APS1), is an important transcriptional regulator." (PMID 30255105, 2018).